ENSG00000260643 (novel protein)
Gene: Protein-coding gene on chromosome 16 (81,053,587 to 81,096,296, reverse strand). Ensembl gene ENSG00000260643.
Genetic constraint (gnomAD): Loss-of-function variants: 1 observed, 2.77 expected, observed/expected ratio (o/e) 0.36, 90% interval 0.12 to 1.54. That is too few expected variants to judge how well the gene tolerates losing a copy. Missense variants: 56 observed, 37.47 expected, observed/expected ratio (o/e) 1.49, 90% interval 1.2 to 1.84. Synonymous variants: 22 observed, 14.72 expected, observed/expected ratio (o/e) 1.49, 90% interval 1.05 to 1.91.